CEP170B (centrosomal protein 170B)
Description:
Plays a role in microtubule organization.
Synonyms: FAM68C; KIAA0284; Cep170R
Tractability: PROTAC: ubiquitination databases record sites on it; its protein half-life has been measured.
Gene: Protein-coding gene on chromosome 14 (104,864,541 to 104,896,770, forward strand). Ensembl gene ENSG00000099814.
Subcellular location: Cytoplasm, cytoskeleton
Subcellular location (Human Protein Atlas): Microtubule ends; Centrosome; Cytosol
Gene Ontology:
Cellular component: cytoskeleton
Genetic constraint (gnomAD): Loss-of-function variants: 55 observed, 100.93 expected, observed/expected ratio (o/e) 0.54, 90% interval 0.44 to 0.68. The synonymous counts are far from expectation, so gnomAD's model fits this gene poorly and the ratio says little. Missense variants: 2,210 observed, 2,037.1 expected, observed/expected ratio (o/e) 1.08, 90% interval 1.05 to 1.12. Synonymous variants: 1,033 observed, 870.77 expected, observed/expected ratio (o/e) 1.19, 90% interval 1.13 to 1.25.
Homologues: Orthologues: macaque CEP170B (97% identical), mouse Cep170b (81% identical), rat Cep170b (80% identical), dog CEP170B (80% identical), pig CEP170B (80% identical), guinea pig CEP170B (78% identical), chimpanzee CEP170B (55% identical), tropical clawed frog cep170b (52% identical), zebrafish cep170bb (43% identical), zebrafish cep170ba (39% identical). Paralogues in human: CEP170 (33% identical).
Diseases named in the same sentence as CEP170B in open-access papers:
CEP170B is named in the same sentence as 6 diseases in open-access papers, as found by Europe PMC text mining. Sharing a sentence is not in itself a finding about the gene and the disease. The quoted sentences say what the papers report.
epilepsy (2 papers, 2021 to 2023). A brain disorder characterized by episodes of abnormally increased neuronal discharge resulting in transient episodes of sensory or motor neurological dysfunction, or psychic dysfunction. "However, in relation to the other two identified hub genes (CEP170B and CTD-3193O13.9), their involvement in epilepsy and other neurological disorders had not been pointed out so far." (PMID 34722763, 2021).
ciliopathy (1 paper, 2021). A genetic disorder of the cellular cilia or the cilia anchoring structures, the basal bodies, or of ciliary function. "We identified 10 genes (STK38L, TUBB2A/B, CCNO, ARL13B, RFX2, RAB23, TUBA1C, CEP170B, and SPATA7) that are established or candidate ciliopathy genes." (PMID 34485842, 2021).
renal carcinoma (1 paper, 2025). A carcinoma arising from the epithelium of the renal parenchyma or the renal pelvis. "Among 15 genes which downregulated in Ureteral sample, as well as the chromatin states closed in their potential regulatory sites, four genes (CEP170B, CHMP4C, KCNN4, and TJP2) are prognostic for renal cancer, that high expression is favorable." (PMID 40034749, 2025).
tumor (2 papers, 2018 to 2025). "Currently, more studies on the relationship between −TIPs and tumor prognosis have been conducted on CAMSAPs and ASPM, while fewer studies have been conducted on the relationship between γ-TuRC, KANSL3 and CEP170B and tumor prognosis, mainly focusing on gliomas." (PMID 41464116, 2025).
CEP170B also shares sentences with these, for which no sentence is quoted: glioma (1 paper); neurological disorders (1).